FAM228A (family with sequence similarity 228 member A)
Synonyms: C2orf84; FLJ30851
Tractability: No criterion of Open Targets' tractability assessment is met for any kind of drug.
Gene: Protein-coding gene on chromosome 2 (24,175,051 to 24,200,849, forward strand). Ensembl gene ENSG00000186453.
Subcellular location (Human Protein Atlas): Nucleoplasm
Gene Ontology:
Molecular function: protein binding
Genetic constraint (gnomAD): Loss-of-function variants: 7 observed, 13.71 expected, observed/expected ratio (o/e) 0.51, 90% interval 0.29 to 0.96. The upper end of that interval is the gene's LOEUF score, 0.96, which puts it in group 4 of 6, group 1 being the genes least tolerant of losing a copy. Missense variants: 209 observed, 216.84 expected, observed/expected ratio (o/e) 0.96, 90% interval 0.86 to 1.08. Synonymous variants: 68 observed, 79.94 expected, observed/expected ratio (o/e) 0.85, 90% interval 0.7 to 1.04.
Homologues: Orthologues: chimpanzee FAM228A (97% identical), macaque FAM228A (91% identical), mouse Fam228a (48% identical), rat Fam228a (47% identical), tropical clawed frog fam228b (18% identical), zebrafish fam228a (11% identical). Paralogues in human: FAM228B (32% identical).